Y_RNA (Y RNA )
Gene: Miscellaneous RNA gene on chromosome 22 (37,013,225 to 37,013,319, forward strand). Ensembl gene ENSG00000252412.
Homologues: Orthologues: chimpanzee Y_RNA (100% identical). Paralogues in human: Y_RNA (88% identical), Y_RNA (87% identical), RNY3 (86% identical), RNY3P1 (86% identical), Y_RNA (86% identical), Y_RNA (85% identical), Y_RNA (84% identical), RNY3P14 (83% identical), Y_RNA (83% identical), RNY3P11 (82% identical), RNY3P16 (82% identical), Y_RNA (82% identical), and 89 more.